INS (insulin)
Diseases named in the same sentence as INS in open-access papers (continued):
Sharing a sentence is not in itself a finding about the gene and the disease.
diabetes (continued). "“After I saw my husband had better sugar control with insulin, I accepted insulin” (5 years of insulin use/ 2 years of having diabetes)." (PMID 24164794, 2013). "Certain studies have reported that the overexpression of Cu/Zn-SOD showed a protective effect against nitric oxide-induced cytotoxicity in human islets and INS-1 insulin-secreting cells and alloxan- and streptozotocin-induced diabetes." (PMID 23408741, 2013). "Metabolic syndrome (MS) and type 2 diabetes mellitus (T2DM) have been associated with insulin-resistance; however, the effective therapies in improving insulin sensitivity are limited." (PMID 23452929, 2013). "We recommend C-peptide measurement in diabetes clinical practice predominantly in insulin-treated patients where there is uncertainty about the underlying diagnosis or consideration of a therapy requiring residual β-cell function for its mechanism of action." (PMID 23413806, 2013). "Optimization of glycemic control in particular in pubertal age through intensified care with improved diabetes education and tailored insulin regimen, can contribute to the reduction of direct diabetes-related costs in this patient group." (PMID 23967077, 2013). "The pancreas of PCOS patients with a family history of type 2 diabetes mellitus (T2DM) has a somewhat limited capacity for increased insulin secretory response to glucose." (PMID 23457541, 2013). "The tendency to withdraw from insulin therapy due to improved glycemic control was higher if the duration of diabetes at initiation was shorter." (PMID 24011395, 2013). "Diabetes in this study was induced by STZ, an alkylating agent that causes DNA damage in beta-cells and subsequent inhibition of insulin biosynthesis and secretion." (PMID 24279645, 2013). "In particular, in the treatment of diabetes, insulin – when required – represents an important source of spending for patients and their families." (PMID 23947294, 2013). "After taking insulin, I become more energetic and more confident in life” (3 years of insulin use/ 12 years of having diabetes)." (PMID 24164794, 2013). "The addition of diabetes mellitus, glucose, insulin, age, gender, the presence of hyperlipidemia or HDL value did not improve this model." (PMID 23658732, 2013). "Diabetes mellitus is a multifactorial disease characterized by chronic hyperglycemia resulting from abnormalities in insulin action and/or insulin secretion." (PMID 24982856, 2013). "Distribution of consumption and cost of different types of insulin according to diabetes type from the Saudi National Diabetes Registry, 2012 data." (PMID 24025198, 2013). "In the present study, the frequency of diabetes and levels of HbA1c were similar in the two groups, but a higher percentage of patients with previous MI on aspirin were treated with insulin." (PMID 23976993, 2013). "“I always refer to these two 'specialists’ (my father and older brother who are on insulin) when it comes to insulin” (6 years of insulin use/ 10 years of having diabetes)." (PMID 24164794, 2013). "At enrollment, diabetes treatment was diet alone in 11 patients, one oral agent in 46, two oral agents in 42, and three medications in 8; insulin was used in 23 (4 patients on insulin alone)." (PMID 24028306, 2013). "Normal glucose and protein metabolism of carnivores affects serum glucose and insulin in ways that resemble diabetes pathology in humans." (PMID 24348462, 2013). "The majority of infants with neonatal diabetes of diverse genetic etiologies are born with reduced birth weight, resulting from lower fetal insulin production, as fetal insulin is a major growth factor in utero." (PMID 23766565, 2013). "These worries were substantiated as almost 50% of diabetes patients on insulin felt that its use restricted their life." (PMID 24164794, 2013). "We hope to demonstrate that a game can be an attractive and effective option for CME on insulin and diabetes." (PMID 23612462, 2013).
diabetes (continued). "The women’s increased awareness of diabetes led to extensive behavioural changes because of modified insulin management and increased number of health service visits." (PMID 24267919, 2013). "Our finding of upregulated GLP1 response in insulin-resistant mice therefore suggests that the metabolic perturbations due to IGT or diabetes compromise the GLP1 effect resulting in reduced responsiveness in these conditions." (PMID 23781322, 2013). "In severe insulin resistant cases the system settles in low pAKT state and glucose uptake is impaired, thus characterized as diabetes." (PMID 24400038, 2013). "MafA knockout mice are viable, but develop diabetes during life as a result of the decreased insulin secretion from beta-cells and alteration of islet architecture." (PMID 23737653, 2013). "Recent meta-analyses in the literature have found improved glycemic control with continuous subcutaneous insulin infusion (CSII) compared with multiple daily injections (MDI) of insulin for patients with diabetes mellitus." (PMID 24079842, 2013). "We then performed the genome partitioning analysis to decompose into two components, i.e. the contribution of the genes involved in insulin pathway and that of the rest of the genome for 11 lipids and diabetes related traits." (PMID 23505390, 2013). "It is increasingly being realized that failure of pancreatic beta cells to secrete enough insulin to adequately compensate for obesity and insulin resistance is the primary defects of type 2 diabetes mellitus (T2DM)." (PMID 23870481, 2013). "In vivo experiments also showed similar effects of diabetes on rat liver delta-5 desaturation and the correcting effect of insulin." (PMID 24195588, 2013). "Type 1 diabetes mellitus is a chronic autoimmune disease resulting from the selective destruction of insulin producing beta cells in the islet of Langerhans." (PMID 23970924, 2013). "Additional drug costs attributable to diabetes are not only related to antidiabetic drugs and insulin but also to other drugs, mainly cardiovascular system and psychotropic drugs (antidepressants and analgesics)." (PMID 23627403, 2013). "NNM systems have been studied as a predictive tool in the area of maintaining desired glucose concentrations using glucose and/or insulin dosing algorithms in patients with diabetes." (PMID 23894489, 2013). "Induction of diabetes in male Wistar rats by STZ led to reduction in the body weight with concomitant decrease in the blood insulin levels and increase in the glucose and HbA1 levels." (PMID 23843977, 2013). "The definite therapy for diabetes include target based hypoglycemic drugs (by enhancing beta cell stimulation or by reducing the gluconeogenesis etc.)alone or in combination with insulin based on type and progression of ailment over the years." (PMID 23822656, 2013). "Insulin resistance, or reduced insulin sensitivity, is the key pathophysiologic defect in type 2 diabetes mellitus, metabolic syndrome and cardiovascular disease." (PMID 24098646, 2013). "Insulin pump therapy in the form of continuous subcutaneous insulin infusion (CSII) was introduced in the 1970s and turned out to ensure better metabolic control of diabetes compared to traditional insulin therapy approaches." (PMID 24347835, 2013). "Among individuals with a diabetes duration of <1 year, 27.27% used OADs in combination with insulin, while 52.28% of individuals with a diabetes duration of ≥10 years used a combination of OADs and insulin." (PMID 23800082, 2013). "Diabetes mellitus (DM) is a syndrome of impaired carbohydrate, fat, and protein metabolism caused by either lack of insulin secretion or decreased sensitivity of the tissues to insulin." (PMID 23506532, 2013). "Diabetes is a metabolic disorder characterized by hyperglycemia due to defects in insulin secretion, insulin function, or both." (PMID 23638297, 2013).
diabetes (continued). "Insulin, secreted from pancreatic B-cells, is an important peptide hormone and usually used for the treatment of diabetes." (PMID 23762265, 2013). "According to one experimental study, diabetes therapies, such as insulin, can decrease the severity of lung injury by inhibiting the serum level of HMGB1 during the acute phase of LPS-induced lung injury." (PMID 23622115, 2013). "The abnormal high concentration of cholesterol in the blood during diabetes is mainly due to the increase in the mobilization of free fatty acids from the peripheral depots, since insulin inhibits the hormone-sensitive lipase." (PMID 23861717, 2013). "Our data showed apparent decrease of serum insulin level a week after alloxan injection and we were convinced about diabetes development." (PMID 25653789, 2013). "“I gained a lot of knowledge from self-reading and relatives who are on insulin” (2 years of insulin use/ 5 years of having diabetes)." (PMID 24164794, 2013). "A higher level of adiponectin level has been reported to increase fatty acid oxidation with subsequent reduction of triglycerides thereby directly sensitizing the body to insulin and reserving IR in animal models of obesity and diabetes 28 and in humans." (PMID 29755881, 2013). "The question in the context of the present review is the extent to which the insulin and IGF signal transduction system is responsible for the effects of obesity and diabetes on cancer risk and progression." (PMID 23983688, 2013). "Diabetes duration increased with the number of OADs used and increased as insulin therapy intensified." (PMID 23800082, 2013). "There are many potential mechanisms for this; zinc is important in regard to metabolic diseases (insulin resistance, metabolic syndrome and diabetes) mainly because it is required for insulin storage in pancreas and stabilizing of insulin hexamers." (PMID 23613929, 2013). "The medical history of two patients revealed an insulin-dependend diabetes and a chronic renal failure in two others." (PMID 24066659, 2013). "Drosophila is a highly promising model for studying feeding, satiety, carbohydrate homeostasis, life span, insulin signaling, and human diseases such as diabetes and obesity." (PMID 24098432, 2013). "Men and women who were taking insulin to manage their diabetes reported checking their blood glucose with a similar daily frequency (μmen = 2.1, 95% CI: 2.0-2.2; μwomen = 2.2, 95% CI: 2.1-2.4) [Data not in tables]." (PMID 24262007, 2013). "Recent research on a small group of patients suggests the addition of exenatide at onset of diabetes to decrease insulin requirement." (PMID 24165454, 2013). "Diabetes mellitus is a metabolic disease characterized by hyperglycemia and disturbances in fat and protein metabolism that results from defects in both insulin secretion and/or insulin action." (PMID 23718315, 2013). "Insulin signaling has been studied in mammals because of relevance to diabetes and other diseases but there are many parallels between mammalian and insect pathways." (PMID 24223128, 2013). "A review on costs of diabetes in France suggested that costs in patients with insulin are about twice as much as in patients treated with oral antidiabetics, which is also consistent with our findings." (PMID 23627403, 2013). "In the clinical study, BBR significantly lowered FBG, hemoglobin A1C, triglyceride, and insulin levels in patients with type 2 diabetes mellitus (T2DM)." (PMID 24205048, 2013). "Of the 86 diabetic subjects, 24 with newly diagnosed diabetes and 12 of the subjects with poor metabolic control received therapies including hypoglycemic agents or insulin, respectively." (PMID 24084731, 2013). "The model accounts for device acquisition costs and costs of NSI management in 4 areas of application where SEDs are currently used: blood collection, infusion, injection and diabetes insulin administration." (PMID 24274747, 2013).
diabetes (continued). "In rodents with diabetes, leptin treatment normalized plasma glucose and increased insulin sensitivity." (PMID 23781317, 2013). "Oral administration of BCM7 for 30 days to rats with STZ-induced diabetes resulted in a significant increase in serum level of insulin, and a decrease in the level of glucagon." (PMID 23658831, 2013). "MSCs are capable of differentiating into functional insulin-producing cells in vitro, which can reverse hyperglycemia in diabetes rats." (PMID 23762850, 2013). "Adiponectin's HMW isomer is the most important correlate of insulin sensitivity, and mutant forms of adiponectin unable to form HMW species are associated with diabetes in man." (PMID 23936666, 2013). "We discuss current observations of cancer in the context of obesity, diabetes, and insulin-lowering medication." (PMID 23573093, 2013). "The severity of the intrauterine growth retardation in patients with INS mutations is similar to that of patients with KATP channel mutations, but diabetes tends to present slightly later, even in late infancy or childhood." (PMID 24051999, 2013). "We studied 940 non-insulin-treated patients (mean±SD age 63.4±11.6 years, 49.0% males) from the longitudinal observational Fremantle Diabetes Study Phase I (FDS1) who were followed for 12.3±5.3 years." (PMID 24019966, 2013). "As participants with Type 1 or Type 2 diabetes and insulin and non-insulin users participated in the focus group interviews together, it was not possible to differentiate the experiences of NSNHEs between these two forms of diabetes or treatments conclusively." (PMID 22825805, 2013). "In HFD/STZ model, HFD initiates a state of insulin resistance followed by the addition of low-dose STZ that induces moderate impairment of insulin secretion, which is a characteristic of the later stage of human type 2 diabetes mellitus." (PMID 24151620, 2013). "The diabetes pre-operatively had been treated with oral agents alone (gastric bypass 53.3 %; adjustable gastric banding 66.1 %), or insulin alone or with oral agents (gastric bypass 43.1 %; adjustable gastric banding 33.1 %)." (PMID 23515973, 2013). "Fourth, the pancreata of KRV+pIC+SS treated rats that remained diabetes-free showed normal islet morphology and insulin staining, and the islets were free of detectable insulitis." (PMID 24147110, 2013). "And as the association between AD and insulin resistance syndrome is gaining attention, insulin/insulin receptor-mediated signal transduction in diabetes is also worth further research." (PMID 24386004, 2013). "Diabetes mellitus (DM) is a complex disease with many metabolic disorders characterized by hyperglycemia and defects in insulin secretion or insulin action." (PMID 23964833, 2013). "Various monogenic pancreatic beta cell diabetes arising from key defects within the insulin secretory pathway results in diabetes, manifesting from early infancy to early adulthood." (PMID 23766565, 2013). "I became less apprehensive and was ready to start on insulin therapy” (2 years of insulin use/ 5 years of having diabetes)." (PMID 24164794, 2013). "The known capacity of IDE to degrade insulin is commonly viewed as mechanistic underpinning of its genetic link to diabetes." (PMID 23826334, 2013). "Hepatic FGFR4 expression is decreased by fasting, increased by insulin, and reduced by streptozotocin-induced diabetes." (PMID 23922646, 2013). "Many diabetes patients prefer more effective insulin with fewer side effects (e.g. insulin analogues) and new insulin-delivery devices (e.g. prefilled insulin pens with shorter needles) that are less invasive and more convenient." (PMID 24164794, 2013). "The plasma insulin and C-peptide levels continued to increase for ten months from the onset of diabetes reaching levels significantly higher than the basal level." (PMID 24279645, 2013).
diabetes (continued). "The development of diabetic ketoacidosis has long been associated with intercurrent illnesses, such as infection, inadequate insulin therapy, ischemia, inflammation, and newly diagnosed diabetes." (PMID 24459592, 2013). "BM is a traditional and functional vegetable for several metabolic diseases, including obesity and diabetes, in which chronic adipose tissue inflammation is regarded as a major factor of impaired insulin sensitivity." (PMID 24358329, 2013). "Depression is more prevalent among females with diabetes than males with diabetes, patients with type 2 versus type 1 diabetes and those who are treated with insulin." (PMID 24238561, 2013). "Humans and animals with diabetes also have many other biochemical changes in addition to altered blood glucose, including elevated advanced glycation end products and altered insulin levels." (PMID 23776627, 2013). "Patients with a diabetes duration of 11–14 years had 15% (€96) higher costs for insulin, but 4.1% (€42) lower costs for SMBUG compared with patients with 8–10 years of diabetes duration." (PMID 23967077, 2013). "β-cells specific Dicer1 deletion results in aberrant pancreas development and neonatal death and its inactivation leads to development of diabetes due to reduced insulin expression." (PMID 23878802, 2013). "As an example, transgenic expression of an HA-reactive TCR on CD4+ (TCR-HA107–119) or CD8+ (CL4-HA512–520) T cells promotes spontaneous diabetes development in mice that additionally express HA under control of the rat insulin promoter (RIP-HA)." (PMID 23691523, 2013). "In the animal studies, leptin receptor mutant db/db mouse is a widely used diabetes model presenting hyperglycemia, hyperlipidemia, obesity, and desensitization of insulin signaling pathway." (PMID 24489534, 2013). "It is associated with obesity, insulin resistance (IR) (reduced tissue sensitivity to insulin action), diabetes mellitus (DM) and metabolic syndrome (MS) and is one of the alterations that characterize nonalcoholic fatty liver disease (NAFLD)." (PMID 24084729, 2013). "Diabetes is a bihormonal disorder involving both inadequate insulin secretion and defective glucagon secretion." (PMID 24315372, 2013). "Diabetes mellitus (DM) is a group of metabolic diseases in which a person has high blood glucose levels resulting from defects in insulin secretion and insulin action." (PMID 23671865, 2013). "The results of the present study showed that 30 units/day of insulin were necessary in pregnant women with diabetes mellitus receiving AGT." (PMID 23533796, 2013). "In persons with diabetes, prolonged elevation of insulin levels often leads to dyslipidemia, a process central to the pathogenesis of atherosclerosis and increasing CVD risk." (PMID 23555584, 2013). "The Hong Kong Diabetes Registry (N = 7,549) showed that mean HbA1c levels were 7.9% (insulin alone) or 8.6% (insulin plus OADs)." (PMID 24011395, 2013). "Self-care of diabetes in daily routine involves insulin administration, decisions around food – choices and intake, physical activity, timing of glucose measurements and analysis as well as response to the results." (PMID 24344648, 2013). "Model 1 was adjusted for age, sex, education, smoking, BMI, the duration of diabetes, insulin use, and any history of heart disease, hypertension, dyslipidaemia or stroke." (PMID 23343405, 2013). "This is a step beyond the SF-36 design, but would aid healthcare providers in assessing the economic effectiveness of insulin degludec compared with currently available diabetes treatments." (PMID 23199058, 2013). "Diabetes is characterized by irregular carbohydrate metabolism when enough insulin is not produced by pancreas, or when body cannot effectively use the insulin produced, resulting in hyperglycemia." (PMID 23613832, 2013). "Type 2 diabetes mellitus is characterized by hyperglycemia, insulin resistance, and an impairment in insulin secretion." (PMID 23762544, 2013).